KRAS (KRas proto-oncogene, GTPase)
Diseases named in the same sentence as KRAS in open-access papers (continued):
Sharing a sentence is not in itself a finding about the gene and the disease.
Skin rash (4 papers, 2009 to 2022). A red eruption of the skin. "TTP and OS to the ≥2nd line cetuximab-containing treatment according to KRAS, BRAF, PIK3CA mutations status, PTEN protein expression, AREG and EREG mRNA expression and grade of skin rash in the whole patient′ population." (PMID 21283802, 2011). "As far as TTP was concerned, the univariate analysis demonstrated significant associations with: i) KRAS mutations (p = 0.001); ii) BRAF mutations (p = 0.001); iii) AREG mRNA expression (p = 0.018); iv) EREG mRNA expression (p = 0.002) and v) the development of moderate severe skin rash (p<0.0001)." (PMID 21283802, 2011). "An obvious question is whether skin rash and KRAS are independent predictors." (PMID 19386128, 2009). "Long before KRAS emerged as a predictive marker for responsiveness to EGFR monoclonal antibody targeted therapy, it was well known that skin rash was a very good surrogate marker for responsiveness to EGFR targeted therapies." (PMID 19386128, 2009). "Multivariate analysis revealed KRAS (Hazard Ratio [HR] 4.3, p<0.0001), BRAF mutation (HR: 5.1, p<0.0001), EREG low expression (HR: 1.6, p = 0.021) and absence of severe/moderate skin rash (HR: 4.0, p<0.0001) as independent prognostic factors for decreased TTP." (PMID 21283802, 2011).
soft tissue sarcoma (4 papers, 2016 to 2023). A malignant neoplasm arising from muscle tissue, adipose tissue, blood vessels, fibrous tissue, or other supportive tissues excluding the bones. "Similar results were shown in a study of 62 soft tissue sarcomas with MGMT methylation 33.9% (21/62) and KRAS mutations 3.7% (2/62)." (PMID 27643594, 2016).
squamous cell anal carcinoma (4 papers, 2014 to 2022). "Epidermal growth factor receptor (EGFR) is usually expressed in squamous cell anal carcinoma (SCAC) and anti-EGFR agents could represent a valid treatment strategy, also considering that KRAS and BRAF mutations are rare events in this type of cancer." (PMID 27886225, 2016). "Moreover, cetuximab may be an effective treatment for anal squamous cell carcinoma because EGFR is overexpressed in many cases, while KRAS, NRAS, and BRAF mutations are not observed in most cases." (PMID 35723765, 2022).
uterine carcinosarcoma (4 papers, 2019 to 2026). A usually aggressive malignant neoplasm arising from the uterine corpus and less often the cervix. "In uterine carcinosarcoma (UCS), PSI values of KRAS E4 showed the strongest positive correlation with PTBP1 mRNA expression levels." (PMID 41368203, 2026).
venous thromboembolism (4 papers, 2018 to 2026). Occlusion of the lumen of a vein by a thrombus that has migrated from a distal site via the blood stream. "Somatic tumor mutations in STK11, KRAS, CTNNB1, KEAP1, CDKN2B and MET, which were reported to be associated with cancer-induced venous thromboembolism in an independent study, were infrequent in OSCC." (PMID 35053621, 2022).
acral melanoma (3 papers, 2023 to 2025). "Strikingly, the study of acral melanoma also identified recurrent driver mutations in RTK/RAS signaling genes, including PTPN11, KIT, NF1, KRAS, and NRAS, all of which are recurrent in human AML (and commonly associated with NPM1c mutations)." (PMID 40773291, 2025). "In acral melanoma, BRAF (9%), NRAS (17%), KRAS (8%), KIT (19%), and NF1 (7%) mutations were detected." (PMID 39564955, 2024).
adenopathy (3 papers, 2022 to 2025). "Previous work has shown that the expression of activating KRAS variants in zebrafish mimics key features of human lymphatic disease, including vessel dysplasia and edema." (PMID 40649904, 2025). "Variables, such as sex, age, differentiation grade, positive adenopathy (pN+), tumor size (pT), tumor location, mucinous component, peritoneal carcinomatosis index (PCI), and KRAS mutational status, were analyzed." (PMID 36013160, 2022).
appendix cancer (3 papers, 2019 to 2022). "We confirmed the MUC2 protein‐suppressive effect of dual drug therapy in explant tissue from KRAS mutated mucinous colon/appendix cancers, demonstrating reduced MUC2 protein and mRNA expression levels at 24 hours." (PMID 31958897, 2020). "Similar changes in ERS protein levels following drug therapy were confirmed in explant tissue from KRAS mutated mucinous colon/appendix cancers." (PMID 31958897, 2020). "The overall inhibitory effects of drug therapy on mucin/MUC2 production was confirmed in colonoid cultures from KRAS mutated colon/appendix cancers." (PMID 31958897, 2020). "We investigated the efficacy of dual MEK‐PI3K drug therapy against KRAS mutated mucin 2 (MUC2)‐secreting LS174T cells and patient‐derived ex vivo and in vivo models of KRAS mutated mucinous colon/appendix cancers." (PMID 31958897, 2020). "We confirmed the therapeutic efficacy of this combination treatment using explant tissue and colonoid cultures derived from primary KRAS mutated mucinous colon/appendix cancers." (PMID 31958897, 2020). "Explant tissues derived from KRAS mutated mucinous colon/appendix cancers demonstrate higher basal ERS‐associated UPR marker levels compared to their non‐mucinous counterparts." (PMID 31958897, 2020).
Barrett’s oesophagus (3 papers, 2011 to 2023). "It is therefore interesting to note that we previously showed co-upregulation of ERK signalling and ETV4 expression in OAC and that genes encoding members of the RAS/ERK signalling cascade such as EGFR and KRAS are often amplified in the transition from Barrett’s oesophagus to adenocarcinoma." (PMID 28859074, 2017). "Notably for the non-cancer-outcome ecDNA biopsies, KRAS was amplified; however, the patient died of causes unrelated to Barrett’s oesophagus 2.84 years after TP-2." (PMID 37046089, 2023).
benign neoplasm of the pancreas (3 papers, 2016 to 2022). "Furthermore, the presence of GNAS and KRAS mutation in circulating ct-DNA can help to distinguish patients with premalignant IPMNs from benign pancreatic tumors." (PMID 35008381, 2022). "Applying a threshold of QVAL >30 to the sample set of the pilot series, KRAS mutations at hotspot codons reported in PDAC were identified in cfDNA plasma samples in 7 of 40 cases (sensitivity 17.5%) with PDAC and in 1 cfDNA of 27 patients with pancreatic benign neoplasms." (PMID 27705932, 2016).
brain cancer (3 papers, 2018 to 2025). A primary or metastatic malignant neoplasm affecting the brain. "Moreover, the high-risk group exhibited better responses to carmustine, KRAS(G12C), cyclophosphamide, and vincristine, which are currently used drugs in clinics for brain cancers." (PMID 38817361, 2024). "For example, miR-128 plays a crucial role in nervous system development by targeting Forkhead Box M1, cAMP response element-binding protein (CREB), splicing factor SC35, and LIM domain kinase 1 (Limk1), and has also been linked to various types of brain cancer via targeting STAT5B and KRAS genes." (PMID 40563979, 2025).
cervical tumors (3 papers, 2015 to 2025). "Our cervical tumor mutational landscape shows that most mutations are found in PIK3CA (E545K, E542K) and KRAS (G12D, G13D) and others in FBXW7 (R465C, R505G, R479Q)." (PMID 26155992, 2015).
chordoma (3 papers, 2011 to 2021). Chordomas are rare malignant tumors arising from embryonic remnants of the notochord in axial skeleton. "Our negativeKRAS/BRAF results are similar to the negativefindings of another study which tested chordomas for KRAS andBRAF mutations and their relationship with theFGFR-RAS/RAF/MEK/ERK-ETS2/brachyury pathway." (PMID 21602918, 2011). "Also, several oncogenes such as BCL2 (11.5-fold), BRAF (9.8-fold), KRAS (4.9-fold), and SRC (2.8-fold) are significantly stronger expressed in the recurrent chordoma cell line." (PMID 34330313, 2021).
chronic lymphatic leukaemia (3 papers, 2017 to 2024). "Additionally, a KRAS mutation was detected in the plasma of patient 13 (G12R), a control patient with a history of chronic lymphatic leukaemia previously negative for KRAS mutation." (PMID 28827745, 2017).
Chylothorax (3 papers, 2022 to 2025). The presence of chyle in the thoracic cavity. "In a LM mouse model, KRAS mutations are associated with a loss of lymphatic valves, which has been proposed to cause chylothorax via retrograde lymph flow into the pleural space." (PMID 40236167, 2025).
Cognitive impairment (3 papers, 2020 to 2024). Abnormal cognition is characterized by deficits in thinking, reasoning, or remembering. "IQs were significantly lower in patients with variants in PTPN11, KRAS, RAF1, and SHOC2, but no specific cognitive impairments were found." (PMID 36012976, 2022).
craniosynostosis (3 papers, 2017 to 2024). Craniosynostosis is defined as the premature fusion of one or more cranial sutures leading to secondary distortion of skull shape resulting in skull deformities with a variable presentation. "Among RASopathies, craniosynostosis appears to be consistently associated with NS and CFC syndrome only, and with mutations limited to PTPN11, SHOC2, KRAS, and BRAF." (PMID 29093661, 2017). "Craniosynostosis has been described in individuals with pathogenic variants in other genes of the RAS/MAPK pathway including BRAF, KRAS, PPP1CB, SHOC2, PTPN11, RAF1, and HRAS." (PMID 37774117, 2024).
cystic neoplasm (3 papers, 2014 to 2025). A benign or malignant neoplasm that contains a single or multiple cystic spaces. "Pancreas-specific KRAS-G12D mutation and TGF alpha overexpression in the liver and pancreas have been separately associated with cystic tumors in previous mouse models." (PMID 41282266, 2025).
developmental delay (3 papers, 2022 to 2024). "KRAS mutations, though rarer, often result in a more severe phenotype, with significant developmental delay and cognitive impairment." (PMID 39596663, 2024). "This is particularly relevant given that certain mutations, such as those in KRAS, are known to be associated with more severe developmental delay phenotypes." (PMID 39596663, 2024). "However, it is considered that the KRAS alternation does not possess any phenotypic effect, although it does influence developmental delay." (PMID 36291422, 2022).
encephalocraniocutaneous lipomatosis (3 papers, 2022 to 2025). A rare neoplastic syndrome characterized by the presence of unilateral lipomas of the cranium, face and neck, and ipsilateral cerebral malformations. "Postzygotic variants in KRAS have been described in oculoectodermal syndrome (OES), encephalocraniocutaneous lipomatosis (ECCL) and epidermal nevus syndrome (ENS)." (PMID 35409398, 2022).
epidermal nevus syndrome (3 papers, 2022 to 2024). A syndrome characterized by lesions occurring on the face, scalp, or neck which consist of congenital hypoplastic malformations of cutaneous structures and which over time undergo verrucous hyperplasia. "In this study, we define the lymphatic phenotype and clinical course of 4 individuals with CCLA identified to express somatic pathogenic KRAS variants, including 3 with epidermal nevus syndromes." (PMID 37154160, 2023). "Here, we detail a unique case of a child exhibiting diffuse spinal nerve root hypertrophy in the context of epidermal nevus syndrome driven by molecularly confirmed KRAS G12D mosaicism, treated with the MEK 1/2 inhibitor selumetinib." (PMID 39385823, 2024). "We defined the lymphatic anomalies in 4 individuals with mosaic, activating KRAS pathogenic variants, 3 with epidermal nevus syndromes and 1 without." (PMID 37154160, 2023).
esophagogastric adenocarcinoma (3 papers, 2016 to 2025). "KRAS mutations are known to be infrequent molecular events in esophagogastric adenocarcinoma." (PMID 27014419, 2016). "KRAS mutations do not appear to be prognostic in gastric or gastroesophageal junction adenocarcinoma." (PMID 26844548, 2016).
gallstones (3 papers, 2010 to 2025). Solid crystalline precipitates in the biliary tract, usually formed in the gallbladder, resulting in the condition of cholelithiasis. "Regarding the molecular changes, KRAS mutations are frequent and early events in tumors associated with APBDJ, but less frequent in carcinomas associated with gallstones." (PMID 29142904, 2017).
gastrointestinal carcinomas (3 papers, 2022 to 2025). "The KRAS G12D mutation is among the most commonly identified KRAS alterations in colorectal and other gastrointestinal carcinomas." (PMID 40927517, 2025).
hepatitis B (3 papers, 2020 to 2023).
histiocytic neoplasm (3 papers, 2024 to 2026). Histiocytic tumors are a heterogeneous group of tumors and tumorlike masses commonly associated with histologically identical extracranial lesions. "KRAS mutations, along with MAP2K1, are frequently found in RDD and likely contribute to its role as a clonal histiocytic neoplasm." (PMID 41552389, 2026).
histiocytic sarcoma (3 papers, 2024 to 2025). An aggressive malignant neoplasm with a poor response to therapy, usually presenting as stage III/IV disease. "In dogs, our team was the first to report MAPK pathway activating mutations in PTPN11 gene encoding the protein SHP2, and KRAS in histiocytic sarcomas." (PMID 39202410, 2024). "In the current study, we report our findings of extensive variation in a mutational hotspot region of exon 3 of PTPN11 in canine HS, including the frequency of mutations in PTPN11/SHP2 and KRAS in canine hemophagocytic histiocytic sarcoma (HHS)." (PMID 39202410, 2024). "On a molecular basis, alterations affecting the RAS/RAF/MAPK signaling cascade - such as KRAS, NRAS, BRAF, and others - are commonly reported in histiocytic sarcoma." (PMID 40901224, 2025).
Histiocytosis (3 papers, 2014 to 2023). An excessive number of histiocytes (tissue macrophages). "The discovery of additional mutations in LCH including A-RAF, N/KRAS, PIK3CA, and gene fusions involving B-RAF, ALK, and NTRK enrich the variegate landscape of the histiocytosis and further complicate the therapeutic choice." (PMID 34944576, 2021).
kidney tumors (3 papers, 2020 to 2022). "KRAS mutations are rare events in kidney tumors, however, it has recently been found to be a characteristic feature of PRNRP as reported by multiple studies, including the current reported cases." (PMID 33023600, 2020).
leiomyoma (3 papers, 2019 to 2021). A well-circumscribed benign smooth muscle neoplasm characterized by the presence of spindle cells with cigar-shaped nuclei, interlacing fascicles, and a whorled pattern. "Loss of the tumor suppressor gene PTEN combined with KRAS mutation are more common in leiomyosarcomas than in leiomyoma." (PMID 33244099, 2020). "Thus, our G12V mice with PTEN loss and KRAS G12V mutations recapitulated the heterogeneity of human atypical leiomyoma that can progress to leiomyosarcoma." (PMID 33244099, 2020).
LEOPARD syndrome (3 papers, 2011 to 2024). "No mutations onthe RAF1 gene were identified in negative cases ofPTPN11, SOS1, and KRAS.Patients #39 and #41 were posteriorly diagnosed with suffering from LEOPARDsyndrome, and in fact, they carried the characteristic mutations on genesPTPN11." (PMID 21526175, 2011).
Li-Fraumeni syndrome (3 papers, 2014 to 2023).
lipoma (3 papers, 2015 to 2025). A benign, usually painless, well-circumscribed lipomatous tumor composed of adipose tissue. "We identified a mosaic c.35G > A (p.Gly12Asp) KRAS mutation in the pigmented verrucous epidermal nevus tissue, the intraneural schwann cells and the lipoma." (PMID 25928347, 2015). "We conclude that KENS, the intraneural Schwann cell proliferation and the lipoma in this individual were caused by a postzygotic and mosaic activating c.35G > A (p.Gly12Asp) KRAS mutation." (PMID 25928347, 2015). "We identified the same c.35G > A (p.Gly12Asp) KRAS mutation in the hyperpigmented verrucous skin tissue, intraneural perineurioma and lipoma." (PMID 25928347, 2015). "One group even detected a c.436G > A (p.Ala146Thr) KRAS mutation in an ECCL patient using high throughput sequencing and Sanger sequencing of DNA extracted from the patient’s scalp lipoma." (PMID 41283481, 2025).
Lymphadenopathy (3 papers, 2016 to 2017). Enlargement (swelling) of a lymph node. "In conclusion, EGFR mutations were associated with ground-glass opacity, KRAS-positive tumors were generally solid and less likely to metastasize to the lung and pleura, and ALK-positive tumors tended to present with lymphadenopathy, extranodal invasion, and lymphangitis." (PMID 27518729, 2016). "KRAS-positive patients and ALK-positive were more likely to have lymphadenopathy, compared to EGFR-positive patients (p = 0.079 and p = 0.003, respectively)." (PMID 27518729, 2016).
malignant mesothelioma (3 papers, 2017 to 2023). A malignant neoplasm of the pleura or peritoneum, arising from mesothelial cells. "Despite these limitations, our findings are in line with previous studies, pointing to an underestimated importance of the RAS pathway in pleura malignant mesothelioma, as suggested by a significantly worse prognosis for patients carrying KRAS mutations." (PMID 37046732, 2023).
malignant pleural mesothelioma (3 papers, 2018 to 2022). A malignant neoplasm that arises from mesothelial cells in the pleura and shows a diffuse growth pattern. "Next, we evaluated the therapeutic potential of co‐targeting PLK1 and FGFR in KRAS‐mutant cancer cells, with KRAS wild‐type cancer cells, malignant pleural mesothelioma (MPM) cells, and non‐transformed normal cells tested in parallel for comparison." (PMID 34369083, 2021).